CDK4 (cyclin dependent kinase 4)
Diseases named in the same sentence as CDK4 in open-access papers (continued):
Sharing a sentence is not in itself a finding about the gene and the disease.
chordoma (continued). "CDK6 may therefore be crucial for maintaining redox homeostasis in chordoma to safeguard against ferroptosis, providing rationale for evaluation of CDK4/6 inhibitors in combination with ferroptosis inducers." (PMID 36387127, 2022). "Besides, as there is a paucity of feasible biomarkers for the evaluation of CDK4/6 inhibitor sensitivity in chordoma, another limitation of this research includes that the criteria for application of Palbociclib in the current case might be controversial." (PMID 38369555, 2024). "Importantly, in chordoma the CDK4/6 regulatory gene CDKN2A (also known as p16) is frequently lost." (PMID 32737414, 2020). "As CDK4/6 inhibitors act synergistically with other targeted therapies against chordoma in vitro, the efficacy of SINE compound combinations with the CDK4/6 inhibitor, abemaciclib, was also assessed." (PMID 36059685, 2022). "Here, we evaluated the tumor efficacy of the CDK4/6 inhibitor palbociclib, as well as the PLK1 inhibitor volasertib, in three chordoma patient-derived xenograft (PDX) models to validate and identify novel therapeutic approaches." (PMID 36505864, 2022). "From a gene expression perspective, CDK4 and CDK6 mRNAs have been detected in all eight chordoma cell lines that were interrogated: U-CH1, U-CH2, U-CH3, U-CH6, U-CH7, U-CH10, U-CH11, and U-CH1243." (PMID 32737414, 2020). "The CDK4/6 inhibitors palbociclib and LY2835219 inhibited chordoma cell growth and proliferation in vitro efficiently." (PMID 30775316, 2019). "For example, CDK6 – but not CDK4 – appears to be a genetic essentiality in some chordoma cell lines." (PMID 36387127, 2022). "A body of such molecular, preclinical, and clinical evidence of interest to chordoma oncogenesis has begun to emerge for several kinases: Epidermal Growth Factor Receptor (EGFR), Cyclin-dependent kinase 4 (CDK4), Cyclin-dependent kinase 6 (CDK6) and the mammalian target of rapamycin (mTOR)." (PMID 32737414, 2020). "Additionally, two currently FDA approved drugs, afatinib and palbociclib (EGFR and CDK4/6 inhibitors, respectively) demonstrated synergy in vitro (CI50 = 0.43) while AZD2014 and afatanib also showed synergy (CI50 = 0.41) against a chordoma cell in vitro." (PMID 32737414, 2020). "In chordomas, the regulatory gene CDKN2A is also frequently lost, and thus, CDK4/6 may be in an over-activated state, although multiple upstream seem to be the input in the dysregulation of CDK4/6 activity." (PMID 36505864, 2022). "Importantly, in chordomas, as well as in our PDX chordoma panel, the CDK4/6 regulatory gene CDKN2A (also known as p16) is frequently lost, leading to the fact that CDK4/6 may be found in an over-activated state." (PMID 36505864, 2022). "Other CDK inhibitors like palbociclib (CDK4 and CDK6) were also able to reduce chordoma cell line proliferation but did not result in any significant reduction in brachyury." (PMID 38786326, 2024).
soft tissue sarcoma (20 papers, 2015 to 2025). A malignant neoplasm arising from muscle tissue, adipose tissue, blood vessels, fibrous tissue, or other supportive tissues excluding the bones. "Increased expression of CDK4 is associated with advanced soft tissue sarcomas and is often observed in many types of cancer." (PMID 32117430, 2019). "Recently, the roles of CDK4 have been reported as follows: i) high CDK4 alterations occur in DDLPS among soft tissue sarcomas, ii) CDK4 alteration correlates with worse overall survival, and iii) the levels of CDK4 and MDM2 are not always consistent." (PMID 39588302, 2024). "Amplification of CDK4 and its cyclin partner CCND1, as well as the deletion of CDKN2A (an inhibitor of CDK4/6), is associated with worse survival in patients with advanced soft tissue sarcomas." (PMID 37298520, 2023). "Advanced adult-type soft-tissue sarcoma, excluding DD-LPS, or bone sarcoma patients, progressing after at least one systemic line, whose tumors overexpressed CDK4, but not CDKN2A at baseline biopsy, were accrued in this single-arm phase II trial (EudraCT number: 2016-004039-19)." (PMID 37875500, 2023). "Clinical data from the GEPIA dataset confirms that CDK4, CCT2, and MGAT1 expression levels are highly correlated with prognosis, and that up-regulation may lead to a significant reduction in survival time in patients with soft tissue sarcoma." (PMID 32117430, 2019).
small cell lung carcinoma (19 papers, 2015 to 2024). Small cell lung cancer (SCLC) is a highly aggressive malignant neoplasm, accounting for 10-15% of lung cancer cases, characterized byrapid growth, and early metastasis. "Predicting the intrinsic insensitivity of some ATC to CDK4/6i might be important because, like RB-deficient tumors in other cancers such as small cell lung cancers (SCLC), they might respond particularly well to genotoxic chemotherapy." (PMID 37964967, 2023). "This idea has been validated clinically in small cell lung cancers that are generally insensitive to CDK4/6i due to their RB1 locus alteration, leading to recent approval by the FDA of trilaciclib for this indication." (PMID 36453028, 2024). "This “positive” side effect was recently observed in phase II trials on patients with small-cell lung cancer receiving the CDK4/6 inhibitor trilaciclib." (PMID 34063457, 2021). "Trilaciclib is a recently approved cyclin-dependent kinase 4/6 inhibitor that is designed to decrease the incidence of chemotherapy-induced myelosuppression in adult patients with extensive-stage small-cell lung cancer receiving chemotherapy." (PMID 34419683, 2021). "CDH18 protein was readily detected in LS8817, LS141, and LS0082 cells, and in the non-small cell lung cancer cell line H1975, all of which senesce following CDK4/6 inhibition." (PMID 29789718, 2018). "Nevertheless, available reports suggest that CDK4 expression is crucial for the development of mammary and small-cell lung carcinomas in mice." (PMID 29464035, 2018). "CDK4 was significantly enriched in cell cycle, measles, small cell lung cancer, and pathways in cancer." (PMID 27818681, 2016). "In addition, the combined application of CDK4/6 inhibitor and immune checkpoint inhibitors enhanced the anti-tumor efficacy of patients with small-cell lung cancer by promoting T cell activation." (PMID 37283799, 2023). "This may explain why overall survival was not enhanced by similar trilaciclib/genotoxic combinations in small cell lung cancer, which are almost always Rb null and therefore insensitive to CDK4/6 inhibitors (in comparison, Rb inactivation is only observed in 7–20% of TNBCs)." (PMID 35037284, 2022). "Meanwhile, the newest CDK4/CDK6 inhibitor, trilaciclib, is being studied in small cell lung cancer (SCLC) and triple-negative breast cancer (TNBC) in a bid to prevent chemotherapy-induced myelosuppression." (PMID 34361615, 2021). "Although CDK4/6 inhibitors have demonstrated a myelo-preserving effect in conjunction with chemotherapy in advanced small-cell lung cancer, it did not appear to improve tumor control." (PMID 35646707, 2022).
Thrombocytopenia (19 papers, 2020 to 2025). A reduction in the number of circulating thrombocytes. "It is worth noting that when abemaciclib was added to endocrine therapy, it was associated with a higher frequency of vomiting, diarrhoea, thrombocytopenia, and increased transaminases compared with other cyclin-dependent kinase 4 and 6 inhibitors." (PMID 40075608, 2025). "The seriousness of adverse drug reactions (leucopenia and thrombocytopenia) associated with CDK4/6 inhibitors (whether as monotherapy or in combination with concomitant drug therapy) was explored through a multivariate logistic regression." (PMID 37895811, 2023). "Thrombocytopenia after RT completion was also correlated with CDK4/6i dose reduction, especially G > 1 (p = 0.004; p = 0.006; OR 10.4, respectively)." (PMID 36765648, 2023). "Thrombocytopenia is another emerging side effect of CDK4/6 i treatment reported in PALOMA−2, PALOMA−3, MONALEESA, and MONARCH−3 trials." (PMID 36135204, 2022). "Initially, there was a plan to administer the cyclin-dependent kinase 4/6 inhibitor (CDK4/6i) abemaciclib, which was ultimately not started due to persistent diarrhea and thrombocytopenia." (PMID 39131728, 2024).
brain tumors (18 papers, 2017 to 2025). "Collectively, our findings indicate a pro-oncogenic role of LOC441204 in tumor cell growth through activation of the β-catenin/p21/cdk4 cascade to act as a potential diagnostic marker or therapeutic target in brain tumor." (PMID 28717243, 2017). "In the “FDA-approved different tumor type” category, brain tumors were the most common cancer category (n = 16, 25.0%) with PD-1/PD-L1 inhibitors (n = 6, 38%), CDK4/6 (n = 3, 19%), and EGFR (n = 3, 19%) inhibitors the most common treatments." (PMID 38461318, 2024). "The population pharmacokinetics and pharmacodynamics of palbociclib, a CDK4/6 inhibitor, were characterized for the first time in children and young adults with recurrent, progressive, and refractory brain tumors." (PMID 39771507, 2024). "CDK4 was, recently, the subject of the pediatric brain tumor consortium study (PBTC-042), in a phase I trial of palboclibin; however, DIPG was excluded." (PMID 37637064, 2023). "Co‐occurrence of BRAFV600E and CDKN2A loss defines a subset of pediatric brain tumors that are responsive to combined treatment with BRAF and CDK4/6 inhibitors." (PMID 33769711, 2021). "Recent studies have demonstrated that CDK4/6 inhibitors effectively reduced cell proliferation and tumor growth in several brain tumors, including GBMs, AT/RTs, medulloblastomas and ependymomas." (PMID 34885226, 2021). "Collectively, these results support LOC441204 promotes cell proliferation in brain tumors through stabilization of β-catenin to activate the β-catenin/p21/cdk4 pathway." (PMID 28717243, 2017). "Meanwhile, CDK4 and CDK6 were identified as the target of miR-124 and sensitizes brain tumor to radiotherapy." (PMID 39865088, 2025). "Notably, important oncogenes involved in brain tumor development are located on these chromosomes, such as PDGFR1 and FGFR2 on chromosome 4, EGFR and MET on chromosome 7, and CDK4 and MDM2 on chromosome 12." (PMID 41323387, 2025). "Furthermore, ongoing trials aim to evaluate the inhibition of checkpoint kinases (e.g., CDK4/6, CDK1/2) alone or in combination with CT drugs in brain tumors including recurrent and refractory SHH, Group 3/Group 4 MBs (NCT02255461, NCT04023669)." (PMID 32164294, 2020). "However, the first-line trials discussed previously either did not enroll patients with brain tumors or enrolled too few to draw any conclusions on clinical efficacy of CDK4/6i in patients with brain metastases." (PMID 37366894, 2023). "A phase 0/2 clinical trial was initiated at the Ivy Brain Tumor Center (Phoenix, AZ, USA) to investigate the potential synergism of LY3214996, an extracellular signal-regulated kinase (ERK) 1/2 inhibitor, and abemaciclib, a CDK4/6 inhibitor, in a recurrent GBM patient population (NCT04391595)." (PMID 36105156, 2022).
esophageal squamous cell carcinoma (18 papers, 2013 to 2026). Esophageal squamous cell carcinoma (ESCC) is a type of esophageal carcinoma (EC) that can affect any part of the esophagus, but is usually located in the upper or middle third. "In the present study, we aimed to investigate the clinical and prognostic values of CDK4 amplification and improve the risk stratification in patients with esophageal squamous cell carcinoma." (PMID 33995474, 2021). "CDK4 is amplified and its protein expression is increased in esophageal squamous cell carcinoma (ESCC), and both of them are associated with the poor survival of ESCC." (PMID 31358010, 2019). "Taken together, CDK4 amplification was identified as an independent prognostic factor for survival, which could be incorporated into the tumor–node–metastasis staging system to refine risk stratification of patients with esophageal squamous cell carcinoma." (PMID 33995474, 2021). "For instance, CDK4/6 inhibitor suppresses cellular growth, induces apoptosis, and also inhibits migration, invasion and metastasis in esophageal squamous cell carcinoma." (PMID 40307228, 2025). "Another study reported that dual CDK4/6 inhibition by palbociclib induced apoptosis and senescence in esophageal squamous cell carcinoma cells." (PMID 36005200, 2022). "The inhibition of cyclin-dependent kinase 4/6 in vivo demonstrated a better erlotinib response to suppress TKI drug resistance in esophageal squamous cell carcinoma." (PMID 31801598, 2019). "CDK4 amplification was found in 8.5% (44/520) of patients with esophageal squamous cell carcinoma." (PMID 33995474, 2021). "CDK4 amplification was analyzed by fluorescence in situ hybridization using tissue microarray consisting of representative tissues of 520 patients with esophageal squamous cell carcinoma, and its correlation with clinicopathological features and clinical outcomes were evaluated." (PMID 33995474, 2021). "Thioridazine (THD), an antagonist of the dopamine receptor D2, is a potent anti-anxiety and anti-psychotic that in combination with radiotherapy promotes G0/G1 phase cell cycle arrest by CDK4 and cyclinD1 downregulation on the esophageal squamous cell carcinoma (ESCC) ECA-109 and TE-1 cell lines." (PMID 32923398, 2020). "Our previous results confirmed that the expression level of PRDM5 is related to the pathological characteristics of tumor size, then we speculate whether the expression of PRDM5 affected CDK4 and thus affected the proliferation ability of esophageal squamous cell carcinoma cells." (PMID 35799142, 2022). "Furthermore, studies have demonstrated that combination therapies can overcome resistance to the cyclin-dependent kinase 4/6 (CDK4/6) inhibitor palbociclib in esophageal squamous cell carcinoma (ESCC) with dysregulation of the FBXO4-cyclin D1 axis." (PMID 40534867, 2025). "Additionally, a study found that miR-1 can impede the growth of esophageal squamous cell carcinoma by downregulating the expression of MET, CDK4, and cyclin D1." (PMID 38504949, 2024).
nasopharyngeal carcinoma (18 papers, 2011 to 2025). A carcinoma arising from the nasopharyngeal epithelium. "The results showed that icaritin downregulated the expression of cyclin D1, CDK2, and CDK4 in a dose-dependent manner, further demonstrating that icaritin caused S-phase arrest in nasopharyngeal carcinoma cells." (PMID 36467051, 2022). "At the same time, the overexpression of CDK4 is a poor prognostic factor of nasopharyngeal carcinoma (NPC) and influences tumor progression by regulating the p21/CCND1/CDK6/E2F1 signaling pathway." (PMID 36292719, 2022). "To get the downstream pathways of COL22A1, we established overexpression of COL22A1 nasopharyngeal carcinoma cells with the addition of the CDK4/6 inhibitor (Palbociclib)." (PMID 36196630, 2022). "Using immunohistochemistry, we analyzed CDK4 protein expression in clinicopathologically characterized nasopharyngeal carcinoma (NPC) cases and nasopharyngeal tissues (NPs)." (PMID 24751144, 2014). "Similarly, let-7C inhibited the cell cycle at G1/S phase by targeting and modulating p15/p16/CDK4/E2F1 pathway of nasopharyngeal carcinoma cells." (PMID 36076967, 2022). "Western blot results showed that nasopharyngeal carcinoma CNE-2Z cells expressed CDK4 and CDK6." (PMID 27451945, 2016). "Overexpression of miR-188 inhibits cell proliferation, tumor colony formation and G1/S cell cycle transition in human nasopharyngeal carcinoma CNE cells by inhibiting CCND1, CCND3, CCNE1, CCNA2, CDK4 and CDK243." (PMID 27708404, 2016).